NEK2 (NIMA related kinase 2)
Description:
Protein kinase which is involved in the control of centrosome separation and bipolar spindle formation in mitotic cells and chromatin condensation in meiotic cells. Regulates centrosome separation (essential for the formation of bipolar spindles and high-fidelity chromosome separation) by phosphorylating centrosomal proteins such as CROCC, CEP250 and NINL, resulting in their displacement from the centrosomes. Regulates kinetochore microtubule attachment stability in mitosis via phosphorylation of NDC80. Involved in regulation of mitotic checkpoint protein complex via phosphorylation of CDC20 and MAD2L1. Plays an active role in chromatin condensation during the first meiotic division through phosphorylation of HMGA2. Phosphorylates: PPP1CC; SGO1; NECAB3 and NPM1. Essential for localization of MAD2L1 to kinetochore and MAPK1 and NPM1 to the centrosome. Phosphorylates CEP68 and CNTLN directly or indirectly. NEK2-mediated phosphorylation of CEP68 promotes CEP68 dissociation from the centrosome and its degradation at the onset of mitosis. Involved in the regulation of centrosome disjunction. Phosphorylates CCDC102B either directly or indirectly which causes CCDC102B to dissociate from the centrosome and allows for centrosome separation. [Isoform 1]: Phosphorylates and activates NEK11 in G1/S-arrested cells. [Isoform 2]: Not present in the nucleolus and, in contrast to isoform 1, does not phosphorylate and activate NEK11 in G1/S-arrested cells.
Synonyms: NEK2A; NLK1; RP67; PPP1R111; HsPK21
Tractability: Small molecule: a structure with a bound ligand is known; a high-quality ligand is known; it has a high-quality binding pocket; it belongs to a druggable protein family. Antibody: its Gene Ontology location is reachable by antibodies, with high confidence. PROTAC: it is named in the literature on targeted protein degradation; ubiquitination databases record sites on it; a small molecule that binds it is known.
Target class: Other protein kinase NEK family; Kinase; Enzyme; Other protein kinase group; Protein Kinase
Chemical probes: MBM-55 (high quality), PD134284, PD134285, PD134286
Gene: Protein-coding gene on chromosome 1 (211,658,657 to 211,675,663, reverse strand). Ensembl gene ENSG00000117650.
Subcellular location: Nucleus (Isoform 1); Nucleus, nucleolus; Cytoplasm; Cytoplasm, cytoskeleton, microtubule organizing center, centrosome; Cytoplasm, cytoskeleton, spindle pole; Chromosome, centromere, kinetochore; Chromosome, centromere; Cytoplasm (Isoform 2); Nucleus (Isoform 4)
Subcellular location (Human Protein Atlas): Centrosome; Nucleoplasm; Basal body; Cytokinetic bridge; Primary cilium
Pathways (Reactome):
Cell Cycle: APC-Cdc20 mediated degradation of Nek2A; AURKA Activation by TPX2; Loss of Nlp from mitotic centrosomes; Loss of proteins required for interphase microtubule organization from the centrosome; Recruitment of NuMA to mitotic centrosomes; Recruitment of mitotic centrosome proteins and complexes; Regulation of PLK1 Activity at G2/M Transition
Disease: Dengue Virus-Host Interactions
Immune System: GSK3B-mediated proteasomal degradation of PD-L1(CD274)
Organelle biogenesis and maintenance: Anchoring of the basal body to the plasma membrane
Gene Ontology:
Molecular function: protein binding; protein kinase activity; protein phosphatase binding; protein serine/threonine kinase activity; ATP binding; protein serine kinase activity
Biological process: centrosome separation; chromosome segregation; negative regulation of centriole-centriole cohesion; positive regulation of telomere maintenance; regulation of attachment of spindle microtubules to kinetochore; regulation of mitotic centrosome separation; centrosome cycle; G2/M transition of mitotic cell cycle; mitotic cell cycle; regulation of mitotic nuclear division; spindle assembly
Cellular component: centrosome; kinetochore; nucleoplasm; protein-containing complex; cytosol; endoplasmic reticulum lumen; nucleus; chromosome, centromeric region; condensed chromosome; condensed nuclear chromosome; cytoplasm; microtubule cytoskeleton; midbody; nuclear lumen; nucleolus; spindle pole
Genetic constraint (gnomAD): Loss-of-function variants: 21 observed, 46.66 expected, observed/expected ratio (o/e) 0.45, 90% interval 0.32 to 0.65. The upper end of that interval is the gene's LOEUF score, 0.65, which puts it in group 2 of 6, group 1 being the genes least tolerant of losing a copy. Missense variants: 368 observed, 501.81 expected, observed/expected ratio (o/e) 0.73, 90% interval 0.67 to 0.8. Synonymous variants: 163 observed, 181.11 expected, observed/expected ratio (o/e) 0.9, 90% interval 0.79 to 1.02.
Homologues: Orthologues: chimpanzee NEK2 (99% identical), macaque NEK2 (98% identical), dog NEK2 (94% identical), pig NEK2 (92% identical), rabbit NEK2 (92% identical), rat Nek2l1 (89% identical), guinea pig NEK2 (89% identical), mouse Nek2 (88% identical), tropical clawed frog nek2 (72% identical), zebrafish nek2 (67% identical). Paralogues in human: NEK5 (29% identical), NEK3 (28% identical), NEK8 (28% identical), NEK11 (27% identical), NEK9 (26% identical), NEK10 (24% identical), NEK7 (22% identical), NEK6 (22% identical).
Diseases named in the same sentence as NEK2 in open-access papers:
NEK2 is named in the same sentence as 111 diseases in open-access papers, as found by Europe PMC text mining. Sharing a sentence is not in itself a finding about the gene and the disease. The quoted sentences say what the papers report.
breast carcinoma (80 papers, 2009 to 2026). "NEK2 loss can inhibit the growth of breast cancer cells, precluding the development of stable, NEK2-deficient cell lines." (PMID 39826695, 2025). "Previous studies have found that CENPF, MELK, PBK, TOP2A and NEK2 are upregulated in breast cancer and this is associated with a poor prognosis." (PMID 36776306, 2023). "For example, NEK2 has an important role in centrosome separation and is implicated in breast cancer progression, while NEK6, NEK7 and NEK9 are involved in mitotic spindle assembly, which requires regulation of microtubule polymerization." (PMID 36550548, 2022). "Our study revealed that among all members of the NEK family, NEK2 is overexpressed in breast cancer patients and is associated with a poor prognosis in breast cancer." (PMID 34834441, 2021). "(iii) Silencing Nek2 with siRNA inhibited proliferation, induced cell death (due to mitotic errors), and dramatically increased the susceptibility of breast cancer cells to DNA-damaging modalities." (PMID 33267874, 2020). "Increased expression of NEK2 causes centrosome amplification in breast cancer cells that express oncogenic K-RAS." (PMID 26320076, 2015). "Furthermore, the overexpression of NEK2 is associated with obese patients with luminal A breast cancer." (PMID 32294979, 2020). "Upregulation of the NEK2/TUFT1 axis in breast cancer is associated with poor outcomes, implying that for the cancer cell population the disadvantage conferred by TUFT1 hyperphosphorylation on cell proliferation may be overcome by its advantage of increasing CA and CIN." (PMID 41022752, 2025). "In addition, overexpression of NEK2 has been demonstrated in many tumors and associated with aggressive cancer phenotype and poor prognosis in pancreatic ductal adenocarcinoma, colorectal carcinoma, cholangiocarcinoma, and breast cancer." (PMID 28881785, 2017). "Among them, PBK and NEK2 were experimentally confirmed to promote tumor cell proliferation, providing novel insights for early diagnosis and therapeutic strategies in breast cancer." (PMID 41727445, 2026). "Analysis of data from The Cancer Genome Atlas (TCGA) revealed that compared to other common mitotic kinase genes, NEK2 is the most frequently amplified and/or overexpressed in breast cancer." (PMID 39826695, 2025). "We mainly focused on cervical and breast cancers for subsequent investigations because both NEK2 and TUFT1 have been reported to promote the progression and chemoresistance of these two cancers." (PMID 41022752, 2025). "We more specifically evaluated NEK2 expression in normal and tumor-adjacent tissues as well as breast cancers in the TCGA dataset and confirmed that NEK2 mRNA is elevated in tumors compared to normal breast tissue." (PMID 39826695, 2025). "We found that NEK2 is more frequently amplified and/or overexpressed in breast cancer than other mitotic kinases and that breast cancer cells are dependent on NEK2 for growth while nontransformed cells are not." (PMID 39826695, 2025). "NEK2 is necessary for the maintenance of chromosomal stability in tumor cells and has previously been reported to be overexpressed in breast cancer cells." (PMID 39826695, 2025). "In summary, upregulation of the NEK2/TUFT1 axis predicts poor outcome in patients with breast cancer." (PMID 41022752, 2025). "In tumors, studies have found that the NEK2 expression increases in a variety of tumors, and NEK2 promotes tumor growth, metastasis, drug resistance and other processes, including breast cancer, lung cancer, colorectal cancer, etc.." (PMID 38503948, 2025). "Previous studies have demonstrated that high levels of NEK2 mRNA and proteins correlate with poor prognosis in patients with breast cancer." (PMID 38886738, 2024). "NEK2 is overexpressed in a variety of human cancers, such as colon cancer, breast cancer, gastric cancer, hepatocellular carcinoma and pancreatic cancer." (PMID 39768163, 2024).
breast carcinoma (continued). "NEK2 overexpression has been linked to TNBC, luminal breast cancer, and HER2-positive breast cancer subtypes." (PMID 38606093, 2024). "As the function of NEK2 varies in luminal, HER2-positive, and TNBC settings, knowing the precise impact of NEK2 dysregulation in distinct breast cancer subtypes can provide important insights for targeted therapy approaches." (PMID 38606093, 2024). "NEK2 is documented to be overexpressed in breast-cancer tissue relative to normal tissue, and is required for the growth, maintenance and survival of the transformed cell." (PMID 37287543, 2023). "Our study confirmed that the expression level of NEK2 was significantly higher in four kinds of breast cancer than in MCF-10A." (PMID 35368696, 2022). "Nek2 overexpression has been described as a prognostic biomarker for disease progression and patient survival in different cancer types, including breast cancer." (PMID 36494865, 2022). "In previous studies, it was demonstrated that the expression of NEK2 was significantly upregulated in a variety of malignant tumors, including breast cancer, colorectal cancer, cervical cancer, lung cancer and glioma." (PMID 35031599, 2022). "In this study, Nek2 also showed a high overall expression in samples from breast cancer patients, which is consistent with our previous studies, as well as other studies highlighting elevated Nek2 gene expression in breast cancer, including the TNBC subtype." (PMID 36494865, 2022). "The involvement of Nek2 in metastasis has been suggested by studies performed in Drosophila and breast cancer models." (PMID 33907253, 2021). "The MetaCore results of this study revealed a high correlation between NEK2 and the cell cycle and metaphase checkpoint pathway in breast cancer development." (PMID 34834441, 2021). "As a result of our investigation, we found that NEK2 consistently has a poor prognosis in breast cancer." (PMID 34834441, 2021). "We used the MetaCore platform to reveal the functions, enrichment pathways, and network analyses of the NEK2 gene in breast cancer." (PMID 34834441, 2021). "Our comprehensive study of 11 members of the current, exploratory NEK gene family reveals that NEK2/6/8 were closely related to the development of breast cancer in humans." (PMID 34834441, 2021). "The TIMER database was used to explore the immunological microenvironment and identified correlations between levels of immune infiltration and expressions of the NEK2 gene in breast cancer." (PMID 34834441, 2021). "The GSEA result also revealed that the high expression of NEK2 groups in the TCGA breast cancer database were significantly correlated with G2M checkpoint, E2F, MYC targets signaling pathways." (PMID 34834441, 2021). "This study found that the NEK2 gene was significantly overexpressed in human breast cancer tissues compared to normal tissues through the TIMER and UALCAN exploration." (PMID 34834441, 2021). "Among these family genes, NEK2/6/8 overexpression had poor prognostic significance in distant metastasis-free survival (DMFS) in breast cancer patients." (PMID 34834441, 2021). "Several NEK genes have also been identified to be linked with breast cancer, such as NEK2 and NEK3 were found to be overexpressed in human breast cancer." (PMID 34834441, 2021). "An investigative analysis of the network interaction between NEK2 and miRNA revealed hsa-miR-1236-3p, hsa-miR-4264, hsa-miR-486-5p, hsa-miR-155-3p, and hsa-miR-6839-3p are co-expressed for breast cancer development." (PMID 34834441, 2021). "To identify the molecular subtypes of breast cancer that overexpress Nek2, we performed bioinformatic analyses using the METABRIC database of 1904 patients with breast cancer." (PMID 33907253, 2021). "Previous studies have also shown that CD4+ T cells significantly inhibit tumor development, neutrophils, and DCs, and our study also revealed correlations of the NEK2 gene with several immune infiltration rate algorithms in breast cancer tissues." (PMID 34834441, 2021).
breast carcinoma (continued). "MicroRNA (miR)-128-3p inhibits the stem-like cell characteristics of breast cancer stem cells (BCSCs) by inhibiting the Wnt signaling pathway via downregulating NEK2, creating a new target for breast cancer treatment." (PMID 34834441, 2021). "In DNA methylation analysis, this study found that the prognostic value of NEK2/6 in a single CpG was significant in breast cancer development." (PMID 34834441, 2021). "In summary, we observed a significant reduction in both migration and invasion of breast cancer cells depleted of Nek2 through siRNA or INH6." (PMID 33907253, 2021). "DNA methylation analysis also concluded that NEK2/6 had the highest level of DNA methylation and a significant prognostic value (likelihood ratio (LR) test p-value < 0.05) in breast cancer." (PMID 34834441, 2021). "Recent reports have consistently identified high expression of NEK2 in various cancer types, including breast cancer, cervical cancer, liver cancer, and lung cancer." (PMID 34712733, 2021). "High levels of NEK2 mRNA were found in those patients, which was correlated with a poor prognosis and breast cancer recurrence." (PMID 32294979, 2020). "Our initial microarray‐based analysis identified differentially expressed NEK2 related to breast cancer and predicted the regulatory microRNA‐128‐3p (miR‐128‐3p)." (PMID 32558224, 2020). "NEK2 has been reported to have a role in the progression of several malignancies, importantly in breast cancer, therefore devising the potential of an anticancer therapy." (PMID 32033228, 2020). "Regarding breast cancer, the authors analyzed 20 human breast cancers, and it was found that NEK2 overexpression was present in the majority of these samples." (PMID 32294979, 2020). "Using bioinformatics tools in our study, we were able to find that NEK2 is highly expressed in breast cancer." (PMID 32558224, 2020). "Collectively, this study defines the potential role of miR‐128‐3p and NEK2 as a therapeutic target in breast cancer treatment by regulating the Wnt signalling pathway." (PMID 32558224, 2020). "In summary, in breast cancer, miR‐128‐3p is likely to influence the development of breast cancer via the Wnt signalling pathway by regulating the NEK2 gene." (PMID 32558224, 2020). "Evidence shows that mitotic regulators including NEK2 are often up‐regulated in cancers, and that up‐regulated NEK2 is correlated with poor survival rate of patients suffering from breast cancer." (PMID 32558224, 2020). "Alternatively, the overexpression of Nek2 in human breast cancer is commonly attributed to the amplification of region 1q32, the locus of the human Nek2 gene." (PMID 33267874, 2020). "The interaction between NEK2 and TRF1 was analyzed by the immunoprecipitation of MCF7 (breast cancer) cells, and the association of both proteins was higher in the G2/M phase." (PMID 32294979, 2020). "In summary, this study indicates that miR‐128‐3p inhibits the stem‐like cell features of BCSCs via inhibition of the Wnt signalling pathway by down‐regulating NEK2, which provides a new target for breast cancer treatment." (PMID 32558224, 2020). "Nek2 is overexpressed in various cancers, including Her2 positive breast cancer, where it predicts poor overall survival." (PMID 33267874, 2020). "High expression of NEK2 also mediates drug resistance to cisplatin or lipo-doxorubicin in myeloma, breast cancer, ovarian cancer and liver cancer." (PMID 35582716, 2019). "E2Fs affect the expression of proteins, including Nek2 and Plk4, thereby deregulation of E2Fs induces centrosome amplification in breast cancer." (PMID 35582716, 2019). "High levels of Nek2 protein and Nek2 mRNA overexpression have been reported in breast cancer and in individual subtypes, making Nek2 a relevant drug target." (PMID 29757235, 2018). "Nek2 functions in the regulation of mitotic spindle formation, chromosome segregation, cell division, carcinogenesis, and the tumorigenic growth of breast cancer." (PMID 29301506, 2018).